EGFR (epidermal growth factor receptor)
Diseases named in the same sentence as EGFR in open-access papers (continued):
Sharing a sentence is not in itself a finding about the gene and the disease.
cancer (continued). "Epidermal growth factor receptor (EGFR) is overexpressed in various types of cancers, and has been found to be overexpressed in CSCs as well, contributing to several characteristics of these TICs, including self-renewal and tumorigenesis." (PMID 34452081, 2021). "Our study highlights a wide-spread reduction in sensitivity to anti-cancer drugs accompanied with an acquired vulnerability to EGFR inhibitors following CDK4/6 inhibitor treatment." (PMID 34944934, 2021). "EGFR-targeting therapy has been used in many other cancers but with limited benefits for GE cancer patients." (PMID 34012400, 2021). "A multi-domain adaptor protein intersectin-s can integrate DENND2B (ST5) to promote the recycling of ligand-free epidermal growth factor receptor (EGFR) to the cell surface that is a reoccurring theme in cancer cell growth." (PMID 34395234, 2021). "Using the Cancer Genome Atlas database of EGFR-mutant LUAD based on the immune score derived from the ESTIMATE algorithm, we divided 80 patients with EGFR-mutant LUAD samples into high and low immune score groups with different immune microenvironments." (PMID 34631565, 2021). "All specimens were from patients who had developed clinical resistance to EGFR inhibitor treatment and whose resistant cancers demonstrated MET amplification as defined by targeted NGS or FISH." (PMID 34516823, 2021). "AFAP1-AS1 can indirectly influence activity of some cancer-related pathways such as EGFR/AKT, Wnt/β-catenin, PTEN/p-AKT, RhoA/Rac2 and PI3K/AKT." (PMID 34912717, 2021). "To mimic this condition, we first cultured cancer cells in LG medium, and immunocytochemically observed EGFR expression predominantly in the cytoplasm, especially in the perinuclear region." (PMID 32901097, 2021). "Our results show that 89Zr-8709-scFv-Fc has the potential to be used for diagnosis, patient selection and treatment monitoring of EGFR-positive cancers." (PMID 33535661, 2021). "Epidermal growth factor (EGF), a specific ligand for epidermal growth factor receptor (EGFR), which is also overexpressed in cancer cells, showed its potential for target delivery." (PMID 34064297, 2021). "Monensin is a Na+ ionophore and has been shown to slow down EGF-induced EGFR degradation in cancer cells." (PMID 34025398, 2021). "Akt hyperactivity is a common hallmark of a variety of human cancers, including EGFR-mutant LUAD, making it an important therapeutic target for cancer treatment." (PMID 33568630, 2021). "GE11 exosomes showed high affinity for epidermal growth factor receptor (EGFR)-overexpressing cancer cells and low mitogenic activity, making them a promising delivery system for EGFR-targeted therapy." (PMID 33537081, 2021). "Gefitinib has been exerted anticancer activities including anti-proliferation, anti-apoptosis, and anti-angiogenesis in several human cancer cell lines with EGFR expression." (PMID 33639651, 2021). "Studies in vitro showed that lapatinib inhibited the proliferation of ErbB2 and EGFR, which are overexpressed in cancer cells." (PMID 34944904, 2021). "These domains are heavily decorated with N-glycans and are involved in cancers notably as a result of aberrant or excessive glycosylation, inappropriate N-glycosylation often resulting in EGFR dysfunction." (PMID 34811416, 2021). "Therapies targeting EGFR are standard in several cancers, and have also been proposed as promising inhibitors of neuroinflammation in the CNS neurodegenerative diseases." (PMID 33368549, 2021). "In this study, we used an antibody targeting the epidermal growth factor receptor (EGRF) labelled with the alpha emitter 213Bi (213Bi-anti-EGFR-MAb), to explore treatment associated responses in two different cancer cell lines expressing EGRF." (PMID 33737524, 2021). "The activation of EGFR pathways activates cancer proliferation and increases metastasis potential, as well as neo-angiogenesis." (PMID 34279406, 2021).
cancer (continued). "As a matter of fact, EGFR/HER signaling pathways regulate almost all aspects in cancer biology including cell growth, survival, adhesion, migration, and differentiation." (PMID 34012400, 2021). "In GBM, EREG enhances the phosphorylation of EGFR, thus activates EGFR signaling and directs cancer cell proliferation." (PMID 33803224, 2021). "EGFR amplification and overexpression is one of the main factors driving cancer development, indicating that EGFR overexpression is related to the generation of resistance to radiotherapy and chemotherapy." (PMID 34766149, 2021). "Both EGFR and E-cadherin are vital for normal development, highly dynamic and often dysregulated in cancer cells." (PMID 35127732, 2021). "For example, the well-recognized cancer-driving EGFR mutation, L858R (c.2573T>G), introduces a 5′–GGGCUGG–3′ to 5′–GGGCGGG–3′ change in the sequence of the EGFR mRNA, creating a potential target for G-rich oligonucleotides." (PMID 34439902, 2021). "Of note, PGRMC1 exists in protein complexes including EGFR and modulates its expression levels in multiple cancer cell lines (breast, lung, colon cancers) and affects their proliferation and chemoresistance." (PMID 34069911, 2021). "Together, these data clearly support the tight association between DR4 reduction and cell response to osimertinib or EGFR-targeted cancer therapy against EGFRm NSCLC cells." (PMID 33664875, 2021). "Here, we characterize the prevalence of ERBB family KDDs across multiple human cancers and evaluate the functional biochemistry of EGFR-KDD as it relates to pathogenesis and potential therapeutic intervention." (PMID 33654076, 2021). "We further screened the activated ligand-receptor pairs between ductal cells and these two stroma-cell types and defined several cancer-associated pairs, such as EGFR/TGFB1, ANXA1/FPR3, EREG/EGFR, and ICAM1/AREG." (PMID 34326696, 2021). "Ras–Raf–Mek pathway is involved in signaling downstream from EGFR leading to the growth of cancer cells and tumor metastasis." (PMID 34781949, 2021). "On the other hand, accumulated evidence has revealed that EGFR promotes cancer cell survival through tyrosine kinase activity-independent mechanisms." (PMID 34267653, 2021). "Both strategies of inhibition of EGFR have been approved for clinical use and have effective anti-cancer activity." (PMID 34512175, 2021). "The LRIG gene family was discovered in a research on EGFR, which plays a critical role in cancer progression." (PMID 33718179, 2021). "YQ456 promoted p‐EGFR stability in cancer cells, thereby increasing the aberrant activation of EGFR pathway, leading to oncogene‐induced senescence (OIS), as evidenced by increased p16Ink4a expression and reduced p‐Rb expression." (PMID 33634965, 2021). "Innovative trials have already explored the potential of novel anti-cancer agents such as the epidermal growth factor receptor (EGFR)-inhibitor lapatinib." (PMID 34046693, 2021). "The area under the curve (AUC) of FN1 expression was 0.875, higher than that of epidermal growth factor receptor (EGFR) expression (AUC = 0.756, p < 0.001), which has been regarded as a biomarker in multiple malignant carcinomas." (PMID 34746236, 2021). "Having confirmed the potency of DpC in inducing NDRG1, we tested its effect on EGFR signaling, as was previously reported in carcinoma models." (PMID 35008802, 2021). "Examination of KRAS and BRAF mutation statuses is indicated in metastatic cases since wildtype KRAS and BRAF carcinomas are eligible for anti-EGFR therapy." (PMID 33671994, 2021). "In carcinoma cells, inhibition of gC1qR with a monoclonal antibody is known to reduce EGFR phosphorylation and block stimulation of migration and formation of lamellipodia in response to EGF." (PMID 34724825, 2021).
cancer (continued). "This is particularly the case of Epidermal Growth Factor Receptor inhibitors (EGFRi) targeting carcinomas." (PMID 33402117, 2021). "Using phospho-peptide affinity chromatography and mass spectrometry, we found that PLCγ1 binds β4 at the phosphorylated residues Y1422/Y1440, but were unable to verify this interaction in A431 carcinoma cells that overexpress the EGFR." (PMID 33883672, 2021). "These ligand-independent EGFR activation pathways are emerging as critical factors in the inevitable development of therapeutic resistance characteristic of most EGFR-driven epithelial carcinomas." (PMID 35083168, 2021). "We found that miR‐1 expression increased after acquiring EGFR‐TKI resistance in carcinoma cells although only one cell line model, revealed by comprehensive miRNA analyses." (PMID 33305905, 2021). "Cinobufagin also strongly inhibited the proliferation of carcinoma cell lines with wild-type or mutant EGFR expression." (PMID 34925034, 2021). "Here we review the epidermal growth factor (EGF), which controls epithelial cells, the precursors of all carcinomas, and the cognate cell surface receptor, called EGFR." (PMID 34206026, 2021). "The choice of the initial profile was guided by biology: dual inhibitors of EGFR and ErbB2 are regarded as an advantageous treatment option for several carcinomas, whereas BRAF is a common undesired anti-target." (PMID 33530327, 2021). "In vitro studies using human carcinoma HEp2 cells that overexpress EGFR demonstrated high cellular uptake, particularly for the cyclic peptide conjugate 5, and low cytotoxicity in light (~1 J·cm−2) and darkness." (PMID 33498632, 2021). "It is well-known that EGFR is overexpressed in over 90% of SCCHN tumors, and close to 10–30% of SCCHN carcinomas demonstrate EGFR gene amplification." (PMID 34298761, 2021). "Since BTC is a kind of carcinoma, drugs that inhibit the epidermal growth factor receptor pathways such as erlotinib, cetuximab or panitumumab had also been used in combination with chemotherapy." (PMID 34359732, 2021). "In this review article, we will first provide a brief overview of EGF receptor (EGFR) structure and function, and its importance as a therapeutic target in epithelial carcinomas." (PMID 35083168, 2021). "The risk of recurrence of Luminal carcinomas can be predicted more accurately with a further evaluation of the Ki67 labelling index and the expression of CK5/6 and EGFR." (PMID 33801360, 2021). "Hyperactivation of STAT3 enhances carcinogenesis in various cancers and drives drug resistance in response to EGFR TKIs." (PMID 32983988, 2020). "The possible mechanisms by which increased β1-6 branched N-antennas enhance cancer progression include the lattice formation via galectin binding to LacNAc, leading to prolonged growth-factor signaling by EGFR." (PMID 32340396, 2020). "EGFR activation regulates the expression of proteins related to cancer cell growth, signaling, differentiation, adhesion, migration, and survival through the MAPK, Akt, and STAT signaling pathways." (PMID 33158043, 2020). "The sE-cad increased the motility and invasion of cancer cells as well as activation of EGFR signal and cell growth." (PMID 33204367, 2020). "Our results avail in the development of virotherapies utilizing CPV against cancers given the functionalities of EGFR in regulating TfR that plays dual roles in CPV entry and Fenton effect as well as in triggering host cell cycle arrest as unveiled here." (PMID 32877289, 2020). "Taken together, high expression of both TRIB3 and EGFR is the biomarker to determine the sensitivity of cancer cells to SAH-JGZ4 treatment." (PMID 32694521, 2020).
cancer (continued). "In particular, neutrophil elastase released from activated neutrophils stimulates protease activating receptor 2 (PAR2) in cancer, leading to the activation of EGFR via HB-EGF and the induction of uncontrolled progression." (PMID 32121107, 2020). "As a potential therapeutic target in TNBC and other cancers, several monoclonal antibodies (mAbs) and TKIs against the EGFR have been developed and tested in breast and other cancer types." (PMID 32784650, 2020). "EGFR-carrying cancer EVs can also interact with endothelial cells directly and reprogram their signaling circuitry and growth factor responses." (PMID 32444772, 2020). "Many drugs are developed for commonly occurring, well studied cancer drivers such as vemurafenib for BRAF V600E and erlotinib for EGFR exon 19 mutations." (PMID 32144301, 2020). "Several reasons as mentioned, therefore, the EGFR protein has been emphasized in various research fields, especially in cancer research area." (PMID 33224225, 2020). "EGFR is frequently overexpressed in various cancers and has emerged as an attractive target for cancer chemotherapy." (PMID 32318334, 2020). "Combinations with ERK/EGFR inhibitors and chemotherapy hold promise for synergistic anti-cancer effects." (PMID 32231055, 2020). "The link between EGFR and activation of PD-L1 plays an important role in preventing cancer cells escaping the immune surveillance and, therefore the progression of cancer." (PMID 33287803, 2020). "In principle, the mutations of EGFR, the low expression of EGFR, and the changes in its ligands are detrimental to the efficacy of anti-EGFR therapy in some cancers." (PMID 32665850, 2020). "Anti-EGFR targeted therapy includes tyrosine kinase inhibitors (TKIs) and monoclonal antibodies that show high anti-tumor activity in some cancers by interrupting signaling pathway." (PMID 32042390, 2020). "We have reported that rearranging the domain order affected the cancer growth inhibitory activity of humanized bsDb targeting EGFR and CD3." (PMID 33255436, 2020). "Studies have also indicated that although the constitutively active mutant of EGFR, EGFR variant III (EGFRvIII), plays critical pro-survival roles in GBM pathogenesis, and it also makes cancer cells more sensitive to EGFR inhibitors." (PMID 32928268, 2020). "Cetuximab, a monoclonal antibody against EGFR, specifically targets EGFR to inhibit its activation, which impedes cancer progression." (PMID 33028804, 2020). "Cancer cells with augmented mitochondrial EGFR exhibited significantly higher resistance to gefitinib than control cells." (PMID 31936895, 2020). "EGFR, a transmembrane receptor that is overexpressed in many cancer types, plays a key role in cellular proliferation." (PMID 33003324, 2020). "Evidence is accumulating for a critical role played by the EGFR-mediated signaling pathway in cell proliferation, survival, angiogenesis, and cancer metastasis." (PMID 32331211, 2020). "According to our observations, disruption of overexpressed EGFR suppresses cancer cell growth, but ultimately leads to the reactivation of pERK and/or pAKT via an EGFR independent mechanism and drug resistance." (PMID 32413049, 2020). "Cell line experiments revealed that CEA expression and cancer dissemination can be affected by EGFR-TKI selection." (PMID 32034239, 2020). "It is well known that EGFR plays a significant role in a number of varied processes in cancer progression such as cell adhesion, cell motility and invasion which are major steps in EMT event." (PMID 31952541, 2020). "It has been reported that the prolyl hydroxylase PHD3 acts as a scaffold protein to interact with endocytic adapter EPS15, promotes the internalization of EGFR and decreases EGFR signaling to inhibit cell proliferation and survival of cancer cells." (PMID 32943616, 2020).
cancer (continued). "CXCL12 binds to CXCR4 and CXCR7 to promote cancer progression and promotes chemoresistance invasion and migration by activating a number of intracellular signaling molecules, including Akt, EGFR, mTOR, NF-κB, and Src." (PMID 32963527, 2020). "An ongoing HCC clinical trial (NCT03329459) consists of determining the effects of combining FATE-NK100, an allogeneic donor-derived natural killer (NK) cell based cancer immunotherapy, with the anti-EGFR MoAb cetuximab." (PMID 32018226, 2020). "Recently, porphyrin-based COFs (P-COFs) were synthesized, which are a potential candidate for the sensitive detection of target cancer markers or living cells (EGFR and living Michigan cancer foundation-7)." (PMID 33330394, 2020). "EGFR-TKIs have become an important treatment for cancer and there are currently three generations of EGFR-TKIs." (PMID 33680007, 2020). "EGFR phosphorylation induces various oncogenic signaling pathways for cell proliferation, invasion, and metabolic reprogramming in many cancer cells." (PMID 32204508, 2020). "Myoferlin expression is increased in a large panel of cancer cells and tumors, where most of the studies described its role in the recycling of membrane receptors (EGFR, IGFR...)." (PMID 32575867, 2020). "EGFR signal pathway involves in angiogenesis, cancer cell proliferation, migration, invasion as well as inhibition to apoptosis." (PMID 33552955, 2020). "Altogether, results in three cell lines with three EGFR TKIs demonstrate that D3 greatly improves the efficacy of existing cancer therapeutics and furthermore reduces resistant rescue by multiple growth factors." (PMID 32066763, 2020). "Consistent with this conclusion, we observed a positive correlation between USP25 and EGFR expression in a panel of cancer types." (PMID 33202887, 2020). "The epidermal growth factor receptor (EGFR) is a major oncogene targeted by anticancer reagents, and many EGFR-tyrosine kinase inhibitors (TKIs) are now widely used in cancer treatment." (PMID 33092268, 2020). "For example, it has been suggested that the activation of ErbB3 or c-Met signaling contributes to the resistance of cancer cells to EGFR-targeting cetuximab." (PMID 32111076, 2020). "Experiments with erlotinib (Tarceva) and the human EGFR-neutralizing mAb225 (non-humanized C225, cetuximab/Erbitux) suggest ligand-dependent EGFR signaling on cancer cells is required." (PMID 32665556, 2020). "The results showed that all the five anti-EGFR sdAbs significantly increased cancer cell apoptosis at the concentration of 50 μg/ml." (PMID 33023595, 2020). "We found that these proteins were mainly enriched in EGFR (HER1) tyrosine kinase inhibitor resistance, regulation of DNA metabolic process, and pathways in cancers, all of which were directly associated with tumorigenesis." (PMID 33376727, 2020). "Members of the epidermal growth factor receptor (EGFR) family and their ligands are involved in cancer pathogenesis." (PMID 32317675, 2020). "Two signaling pathways were used as models to validate our methods: beta-adrenergic agonistic activity on cAMP generation (dedicated dataset generated for this study) and EGFR inhibitory effect on cancer cell viability." (PMID 32541899, 2020). "Prior clinical investigations showed that EGFR inhibition sensitizes cancer cells to RT and improves locoregional cancer control." (PMID 32143669, 2020). "EGFR overexpression results in activation of tyrosine kinase activity, triggering intracellular pathways resulting in apoptosis blocking, cancer-cell proliferation, invasion, metastasis and neovascularization." (PMID 36046069, 2020). "Further study is required to examine the mechanisms how these anti-EGFR sdAbs inhibit cancer cell growth." (PMID 33023595, 2020).